SNHG21 (small nucleolar RNA host gene 21)
Synonyms: SCARNA15HG; FSD2-AS1; RP11-752G15.6
Gene: Long non-coding RNA gene on chromosome 15 (82,750,512 to 82,796,682, forward strand). Ensembl gene ENSG00000250988.
Gene Ontology:
Biological process: RNA processing
Cellular component: Cajal body; nucleolus
Diseases named in the same sentence as SNHG21 in open-access papers:
SNHG21 is named in the same sentence as 2 diseases in open-access papers, as found by Europe PMC text mining. Sharing a sentence is not in itself a finding about the gene and the disease. The quoted sentences say what the papers report.
hepatocellular carcinoma (1 paper, 2024). A malignant tumor that arises from hepatocytes. "The gene SNHG21 is a low risk gene in hepatocellular carcinoma." (PMID 39758420, 2024).
SNHG21 also shares sentences with these, for which no sentence is quoted: prostate carcinoma (1 paper).